CXCR5 (C-X-C motif chemokine receptor 5)
Diseases named in the same sentence as CXCR5 in open-access papers (continued):
Sharing a sentence is not in itself a finding about the gene and the disease.
lupus (48 papers, 2011 to 2025). "The CXCL10/CXCR3 and CXCL13/CXCR5 axes are associated with disease activity in several autoimmune diseases including rheumatoid arthritis (RA), systemic lupus erythematosus (SLE) and adult onset Still’s disease." (PMID 29116188, 2017). "The critical roles of CXCL13 and CXCR5+ cells in the pathogenesis of LN are also evidenced by studies of anti-CXCL13 neutralizing antibodies in MRL/lpr lupus-prone mice and CXCR5-deficiency in B6/lpr lupus-prone mice." (PMID 27403037, 2016). "Sanroque mice develop lupus-like autoimmunity that is associated with greatly increased numbers of CD4+CXCR5+ T cells and enhanced expression of IL-21." (PMID 23638156, 2013). "Studies have shown that CD4+CXCR5+ cell percentage in CD4+T cells is elevated in the blood of patients with autoimmune diseases such as Systemic Lupus Erythematosus (SLE) and Myasthenia Gravis (MG) and is associated with antibody production." (PMID 34630268, 2021). "This includes CXCR4+ extrafollicular helper T cells in murine lupus, as well as CXCR5− Tfh-like cells in lungs of mice with chronic Ag-driven inflammation, and T resident helper cells observed in lungs of mice with influenza." (PMID 40964009, 2025). "Follicular helper T cells (Tfh), a critical subset of CD4+ T cells in lupus, are characterized by high expression of CXCR5, PD-1, interleukin-21 (IL-21), and the specific transcription factor BCL6." (PMID 40989817, 2025). "Of note, the analysis of non-TFH CD4 + T helper cells (defined as CD45+ CD19– TCRβ+ CD8α– CD4+ CD44+ CXCR5 – cells) revealed that basophil depletion in lupus-like models impacted only the TH2 cell compartment in both mouse models." (PMID 38649353, 2024). "The frequency of circulating CD4+CXCR5+ T cells was found to increase in systemic lupus erythematosus, Sjögren's syndrome, rheumatoid arthritis, juvenile dermatomyositis, Graves’ disease, and myasthenia gravis." (PMID 38383066, 2024). "Mesenchymal stem cells (MSCs) ameliorated lupus symptoms in B6.lpr mice by producing iNOS to decrease CXCR5+PD-1hi Tfh cell expansion." (PMID 37187757, 2023). "CXCR5+PD1+CD4+ T cells were detected at much lower frequencies in lupus-prone MRL/lpr mice that had been treated from eight to 20 weeks of age, However, these T cells were not affected in MRL/lpr mice treated with CGS-21680 after disease onset." (PMID 35064115, 2022). "And then there are the potent TPH cells with TFH like phenotype but are CXCR5-; they help lupus B cells also by producing IL-21; and IL-10–producing CCR6+T cells populate lymph nodes of SLE patients." (PMID 33936042, 2021). "Several investigations have found elevated expression of circulating CXCR5+CD4+ T cells in patients with autoimmune diseases (such as systemic lupus erythematosus (SLE) and Sjogren's syndrome) and infectious diseases (such as hepatitis B and C)." (PMID 30402448, 2018). "Besides, the accumulation of CXCR5‐expressing TH cells positively correlates with disease severity in patients suffering from systemic lupus erythematosus, Sjögren's syndrome, and rheumatoid arthritis." (PMID 33226189, 2021). "Furthermore, γδ T cells from mice with pristane-induced lupus also had increased CXCR5 expression compared to naïve mice." (PMID 30089795, 2018). "Therefore, CXCL13/CXCR5 contributes to the development of LN both systemically in immune tissues and locally in the kidney of lupus-prone mice." (PMID 27403037, 2016). "Similar to what was observed in the SRBC-immunized BALB/c mice, blocking ICOS signaling led to a significant decrease in number of both GC B cells (∼65% reduction, p<0.01) and Tfh (CD4+ CD44high CXCR5+Bcl6+) cells (∼70% reduction, p<0.01) in this spontaneous autoimmune model of lupus." (PMID 25101629, 2014). "Another agent, PF-06835375, a humanized monoclonal antibody against CXCR5, has advanced to Phase I clinical trials in systemic lupus erythematosus (SLE) and rheumatoid arthritis." (PMID 40986007, 2025).
lupus (continued). "In our study, we provide a more detailed phenotypic description of such cells, finding that they belong to the CXCR5- subgroup that is thought to constitute the extrafollicular DN2 subset in active Systemic lupus erythematosus (SLE)." (PMID 36761741, 2023). "While in lupus two DN populations were originally described DN1 CXCR5+CD11c- and DN2 CXCR5-CD11c+, additional DN3 CXCR5-CD11c-have also been described in COVID-19, SLE and autoimmune fibrosis." (PMID 39444662, 2024). "In lupus murine models, the percentage of Tfh cells increased and the Tfr (CD4+CXCR5+FoxP3+) cells decreased in 16-week-old MRL/lpr mice." (PMID 37771588, 2023). "Another interesting finding was that ABCs were better than follicular B cells at priming OT-II cells into CXCR5+ follicular helper T (Tfh)-like cells in in vitro co-culture, while ABC generation preceded Tfh expansion in the CD19cre Shipfl/fl lupus model." (PMID 36072594, 2022). "Those FoxP3-Ly49+(CD158e+ in humans)CD122hiHelios+CXCR5+ CD8 Treg cells were decreased as a percentage of total CD8 T cell population in lupus, but such changes in proportion could be due to many reasons that cause shifts in various CD8 T cell subsets in lupus." (PMID 33936042, 2021). "Research indicates that CXCR5 is pivotal in the advancement of lupus by modulating the movement of B cells and double‐negative (DN) T cells, thereby promoting GC development and directing pathogenic DN T cells toward lymphoid organs and kidneys." (PMID 39835879, 2025). "Renal macrophages and DC in lupus-prone mice may be the source of CXCL13 in the nephritic kidney, leading to increased migration of CXCR5+ B cells and TFH-like cells into the inflamed kidney towards CXCL13." (PMID 27403037, 2016). "In two commonly used lupus-prone mouse models, NZB/W F1 and MRL/lpr, transcript levels of renal CXCL13 and CXCR5 are consistently increased in aged lupus nephritic mice compared to nonlupus control mice or young mice prior to disease onset, suggesting their involvement in the development of LN." (PMID 27403037, 2016). "In lupus, an increase of circulating CD4+CXCR5 + PD-1high T lymphocytes was evidenced in patients with a more severe disease phenotype and a correlation between the expansion of both circulating CXCR5 + Bcl6 + CD4+ T cells and circulating GC B cells was reported." (PMID 24069401, 2013). "Whereas its high expression may also reflect their localization into GC31, CXCR5 levels on TFH cells were not modified by basophil depletion in both lupus-like mouse models." (PMID 38649353, 2024). "Under these conditions, they express CXCR5; enter B cell follicles; present self-antigens to FDC and TFH; initiate GC reactions against self-antigens and contribute to autoimmune diseases such as systemic lupus erythematosus (SLE), Sjögren’s syndrome (SS) and rheumatoid arthritis (RA)." (PMID 39772034, 2024). "CXCR5-PD-1hi Tph cells cocultured with class-switch memory B cells in the presence of TGF-β3 revealed much class-switch memory B cells differentiated into plasmocytes and high expression of IgG and IgM, suggesting that TGF-β3 regulates differentiation and function of Tph-like cells in lupus." (PMID 38164134, 2023). "DN B cells were further divided into two subgroups in a previous study on systemic lupus erythematosus (SLE), DN1 cells (CXCR5+ CD19+ IgD-CD27-) and DN2 cells (CXCR5- CD19+IgD- CD27-)." (PMID 34394101, 2021). "ICOS+PD-1+CXCR5+CD4+ T cells are correlated with the functional properties of Tfh cells and play a role in severe systemic lupus erythematosus (SLE)." (PMID 26517519, 2015). "Simpson and colleagues found that high frequency of peripheral blood TFH cells was detected in patients with active systemic lupus erythematosus (SLE) and Sjogren's syndrome (SS) and they also expressed ICOS, CXCR5, and PD-1." (PMID 21750724, 2011).
lupus (continued). "An increased frequency of DN3 B cells with low expression of CXCR5 was reported in severe COVID-19 identified in CD11c- and CD21− DN B cells, in autoimmune-fibrosis, in chronic cutaneous lupus, and increased early after Rituximab treatment in SLE." (PMID 39444662, 2024). "B cells that are double negative for CD27 and IgD, express CD11c, and are negative for CXCR5 (DN2 cells) have been described to be autoreactive and expanded in lupus." (PMID 37492569, 2023). "In a representative experiment, we found that, unlike CCR6, CCR7 and CXCR5, the surface expression of CXCR4 was substantially up-regulated on the surface of B cells of lupus mice compared with the control non-lupus mice." (PMID 25909640, 2015). "The analysis of peripheral blood B cells by flow cytometry showed that the surface expression of CXCR4 was up-regulated on the surface of B cells of lupus mice, whereas there was no detectable change in the surface expression of CCR6, CCR7 and CXCR5." (PMID 25909640, 2015). "In lupus patients, immature B cells are regulated by sensors of viral RNA such as TLR-7 and can differentiate into extra-follicular double-negative memory B cells (CXCR5-CD11c+)." (PMID 39917309, 2025). "This review focuses on ABC and ABC-like sub-populations found in Systemic Lupus Erythematosus (SLE) patients (such as the double negative 2;DN2 population: CD19+,IgD−,CD27−, CXCR5−,T-bet+) and broaches the subject of their potential use as prognostic and/or diagnostic markers." (PMID 33163863, 2020).
influenza (47 papers, 2013 to 2025). An acute viral infection of the respiratory tract, occurring in isolated cases, in epidemics, or in pandemics; it is caused by serologically different strains of viruses (influenzaviruses) designated A, B, and C, has a 3-day incubation period, and usually lasts for 3 to 10 days. "In any case, these findings provide evidence that both TFH1 ICOS+ and antigen-specific CD4+IL-21+ICOS+CXCR5+ TFH cell subsets are associated with functional antibody responses to influenza vaccination." (PMID 27336786, 2016). "Although the numbers of BCL6-expressing CXCR5+ GC Tfh cells were highest in LCMV-primed mice, the amount of BCL6 expression in tetramer+ CXCR5+ cells was significantly lower than in both GP-primed mice and after primary influenza infection." (PMID 39283916, 2024). "Heterologous infection or immunization priming prior to influenza infection induced increased frequencies and numbers of effector tetramer+ CXCR5–TBET+ Th1 cells compared to both primary influenza infection alone and influenza-immune mice at 8 dpi." (PMID 39283916, 2024). "The expression of CXCR4 was also higher on circulating TFH-like cells from older people 7 d after seasonal influenza vaccination compared with younger individuals, with CXCR5 expression being consistent between the age groups." (PMID 37217705, 2023). "These ferret specific CXCR5 and PD-1 antibodies provide a starting point to allow in-depth study of the Tfh responses to viral infections, such as influenza and SARS-CoV2." (PMID 33479388, 2021). "We analyzed CXCR5+PD-1high expression on total CD4+ T cells in a small subset of influenza+ patients and also found very low levels in the blood at both acute and follow-up timepoints (0-0.2%)." (PMID 33976217, 2021). "Strikingly, hybrid Th1/Tfh cells (ICOS+CXCR3+CXCR5+) did correlate with antibody levels in influenza, where they were also shown to contain IFN-γ+IL-21+ T cells." (PMID 32634740, 2020). "We report that LAIV induced early (3–7 days post-vaccination) activation of tonsillar follicles and influenza-specific TFH-cell (CXCR5+CD57+CD4+ T cell) responses in children, and to a lesser extent in adults." (PMID 31250024, 2020). "This expansion of ICOS+CD38+CXCR5+PD-1+ cTfh cells correlated positively with the increase in influenza-specific antibodies 7 and 42 d after vaccination." (PMID 31175140, 2019). "The data support the use of QIV for immunisation of PLWH, reveal distinct circulating CD4+CXCR5+ T cell subsets and demonstrate oral fluid sampling for influenza-specific IgG is an alternative to phlebotomy." (PMID 31666568, 2019). "To gain insight into how vaccines qualitatively alter Tfh cell responses, we performed RNA sequencing of 200 ICOS+CD38+CXCR5+PD-1+ cTfh cells immediately before and 7 d after influenza vaccination in four individuals." (PMID 31175140, 2019). "Similar increases in blood CXCR3+CXCR5+ICOS+ Tfh cells occurred 7 days after influenza vaccination and correlated with anti-influenza antibody and plasmablast production." (PMID 29904381, 2018). "A subset of circulating ICOS+CXCR3+CXCR5+ TFH cells was reported to play a crucial part in inducing antibody responses in seasonal influenza vaccine trials." (PMID 28533093, 2017). "CXCR5+PD-1+ Tfh percentages and total numbers are higher in aged groups both prior to and during influenza infection." (PMID 27177221, 2016). "However, CXCR5+ CD8+ T cells have been shown to shape antibody responses in mouse models of influenza vaccination." (PMID 38637558, 2024). "We found that heterologous influenza rechallenge resulted in significant increases in the numbers of polyclonal effector antigen-specific CXCR5– Th1 cells in both rGP- and LCMV-primed mice, as well as CXCR5+BCL6+ GC Tfh cells in LCMV-primed mice compared to primary influenza infection." (PMID 39283916, 2024).
influenza (continued). "In addition, after stimulating CD4+CXCR5+Tfh cells with an influenza antigen, it was found that the level of CD40 L in the OS group was significantly reduced and the level of IFNγ was increased considerably." (PMID 35494526, 2022). "Similarly, we examined the surface expression of the chemokine receptors CCR6, CXCR3 and CXCR5 and found a general decrease in the frequency of CXCR5+ cells for all autoreactive as well as the influenza-specific T cells at follow-up." (PMID 32423478, 2020). "Next, we tested whether CXCR5+PD-1+++ cTfh expansion correlated more with vaccination-induced long-term IgG responses measured after influenza and P27A vaccination, as long-term antibody responses are GC derived." (PMID 31175140, 2019). "Here, we have used a seasonal influenza vaccination study and analyses of CXCR5+ Tfh cell populations from the blood and LNs of human donors to refine our understanding of cTfh cells as circulating biomarkers of bona fide Tfh cells resident in secondary lymphoid tissues." (PMID 31175140, 2019). "Similarly, a recent study showed that emergence of plasmablasts and ICOS+CXCR3+CXCR5+CD4+ T cells in blood peaked on day 7 after influenza vaccination." (PMID 30055570, 2018). "A previous study has shown that CXCR4+CXCR5+ double-positive Tfh cells arise following influenza infection and could be identified within the GC43." (PMID 28303891, 2017). "In HIV seronegative individuals, the emergence of blood ICOS+CXCR5+CXCR3+ TFH that are able to produce IL-21 correlated with influenza-specific B cell responses and blood ICOS+IL-21+ influenza-specific TFH expand after immunization and correlate to antibody responses." (PMID 28082992, 2016). "Extensive surface phenotyping was performed together with combinatorial tetramer staining to measure the frequency, memory status (CD45RA and CCR7), chemokine receptor expression (CXCR3, CCR4, CCR6 and CXCR5) as well as activation status (CD38) of these influenza-specific T cells." (PMID 27571776, 2016). "Interestingly, when examined for influenza specificity, CXCR5+ Tfh-like cells were enriched for reactivity to HA, whereas CXCR5− non-Tfh cells were preferentially reactive to NP." (PMID 26834750, 2016). "The IL-2+ producing T cell bias was not due to overlap of the IL-2+ T cells with T follicular helper (Tfh) cells, as the majority of both IFNγ+TNFα+ and IFNγ−IL-2+TNFα+ influenza-specific cells responding to CA/09 and NC/99 were found within the CXCR5− CD4 T cell population." (PMID 23526940, 2013). "We first examined PBMC samples isolated from the five volunteers who had received the 2013–2014 influenza vaccine to identify the subsets of circulating CXCR5+CD4+ Tfh-like cellular populations as control experiments to determine whether different subsets could be identified." (PMID 26333070, 2015). "For this, we analyzed TFH (CD4+CD44+CXCR5+PD-1+) cells compared to Teff (CD4+CD44+CXCR5−PD-1−) cells following LCMV, influenza, T. muris, H. polygyrus and C. rodentium infection." (PMID 40926076, 2025). "We next analyzed I-Ab:gp66-77 tetramer+ CD4+ T cells for CXCR5, PD-1, and BCL6 expression following influenza infection in medLN to determine the kinetics of memory antigen-specific Tfh cells." (PMID 39283916, 2024). "Overall, dynamics of the three cTFH cell subpopulations (cTFH1 [CD3+CD4+CXCR5+CXCR3+CCR6−], cTFH2 [CD3+CD4+CXCR5+CXCR3−CCR6−], and cTFH17 [CD3+CD4+CXCR5+CXCR3−CCR6+]) differed after influenza vaccination." (PMID 36705404, 2023). "To determine which type of antigens induce CXCR5+PD‐1+ CD8 T cells, we used tetramers to study antigen‐specific CD8 T cells toward influenza (FLU), cytomegalovirus (CMV) or Epstein–Barr virus (EBV) by flow cytometry." (PMID 33098668, 2021). "CXCR5 expressing cells on the other hand were mainly detected among CILP/fibrinogen- and influenza-specific T cells and rather less among cells recognizing α-enolase." (PMID 32423478, 2020).